DLL4 (delta like canonical Notch ligand 4)
Diseases named in the same sentence as DLL4 in open-access papers (continued):
Sharing a sentence is not in itself a finding about the gene and the disease.
Lewis lung carcinoma (3 papers, 2012 to 2017). "To test if the vascular normalization induced by Dll4 overexpression had an impact on tumor drug delivery and the formation of distant site metastasis, we used a subcutaneous Lewis Lung Carcinoma (LLC) tumour transplant mouse model." (PMID 28288569, 2017). "Lewis lung carcinoma cells (LLC) were transduced with an empty vector retrovirus (LLC-EV), JAG1-encoded retrovirus (LLC-JAG1) or DLL4-encoded retrovirus (LLC-DLL4) and implanted subcutaneously into C57black/6 Lgals3+/+ or Lgals3−/− mice." (PMID 28533486, 2017).
liver cancer (3 papers, 2020 to 2024). An epithelial or non-epithelial malignant neoplasm that arises from the liver.
liver fibrosis (3 papers, 2015 to 2025). "In summary, we show that liver fibrosis could promote T-cell development by upregulating Dll4 and SDF-1 in liver tissues." (PMID 31165736, 2019). "Together, these results demonstrated that liver fibrosis could upregulate Dll4 expression in hepatocytes, and this expression of Dll4 contributes to the early stage T-cell development by promoting T-cell progenitor development." (PMID 31165736, 2019). "Furthermore, Notch ligands (Dll1, Dll4, Jag1) and downstream molecule (Hes1) were also significantly induced in fibrotic mice versus olive-oil treated non-fibrotic control livers signifying the role of Notch pathway in liver fibrosis." (PMID 26658360, 2015). "Delta-like protein 4 (DLL4), a ligand of the Notch signaling pathway, is highly elevated in LSECs in liver fibrosis." (PMID 40761743, 2025).
nasopharyngeal carcinoma (3 papers, 2014 to 2017). A carcinoma arising from the nasopharyngeal epithelium. "Previous studies observed that Dll4 expression was an independent indicator of poor prognosis in several types of human cancer, including lung, breast, bladder and nasopharyngeal cancer." (PMID 25364440, 2014).
ovarian tumor (3 papers, 2017 to 2022). "Moreover, muzzling Dll4 reaction with Dll4 siRNA repressed explosion of ovarian tumor cells by 2.1-fold associated with the regulation." (PMID 35406423, 2022). "Enoticumab (REGN421) is an anti-DLL4 antibody which is used in DLL4 over expressed ovarian tumors." (PMID 31810474, 2019). "Moreover, Demcizumab as an anti-DLL4 antibody has been also used in advanced ovarian tumors." (PMID 31810474, 2019).
papilloma (3 papers, 2015 to 2021). A benign epithelial neoplasm that projects above the surrounding epithelial surface and consists of villous or arborescent outgrowths of fibrovascular stroma. "The results showed that partial DLL4/Notch inhibition by haploid deletion of DLL4 in papillomas (DLL4+/−) promotes the formation of less mature, but nevertheless productive angiogenesis in skin papillomas." (PMID 34944837, 2021). "In early papillomas, lower levels of Dll4 increase vascularization through change in VEGFR2 levels and consequently enhance sensitivity to endogenous levels of VEGF." (PMID 26314892, 2015). "To study the molecular changes underlining morphological and functional vessel alterations caused by increased Dll4 expression, we used qRTPCR and analyzed D4BE and D4OE papillomas for differential expression of the main genes implicated in angiogenesis regulation." (PMID 28288569, 2017). "Thus, in early papillomas, lower levels of Dll4 increase vascularization through raised VEGFR2 levels, enhancing sensitivity to endogenous levels of VEGF, promoting functional angiogenesis and tumor growth." (PMID 26314892, 2015). "Compared to D4BE papillomas, D4OE tumors had on average 2.8-fold increased Dll4 mRNA levels and 2.5-fold up-regulated Hey2 transcription confirming the Dll4/Notch pathway over-induction." (PMID 28288569, 2017).
sarcoma (3 papers, 2008 to 2020). A usually aggressive malignant neoplasm of the soft tissue or bone. "In mouse sarcoma models, Dll4 knockout or Dll4 blocking antibodies suppressed tumor growth and induced poor development of blood vessels, lumen shutdown, and insufficient blood perfusion." (PMID 31093499, 2019). "For example, the growth of a sarcoma model that is very resistant to VEGF blockade was strongly inhibited by blockade of Dll4-Notch." (PMID 18827808, 2008).
Sepsis (3 papers, 2024 to 2025). Sepsis is defined as life-threatening organ dysfunction caused by a dysregulated host response to infection. "Excessive neutrophil activation is hallmark in sepsis-induced tissue damage and organ dysfunction, highlighting the significance of targeting harmful neutrophil subpopulations such as DLL4+ neutrophils to mitigate ALI." (PMID 41392977, 2025). "In sepsis, DLL4+ neutrophils increase in the blood and lungs, upregulating ZBP1, cleaved gasdermin D, cleaved caspase-3, and phosphorylated MLKL, all of which are markers of PANoptosis, exacerbating ALI." (PMID 41392977, 2025). "To test this, we adoptively transferred DLL4+ or DLL4– neutrophils into the mice concurrent with CLP-induced sepsis." (PMID 41392977, 2025). "During sepsis, eCIRP-induced DLL4+ neutrophils exist in blood circulation and organs, such as lungs." (PMID 41392977, 2025). "We found that, compared with the sham and DLL4– neutrophils/sepsis groups, the DLL4+ neutrophils/sepsis group had significantly higher ZBP1 mRNA and protein expression, whereas NDI effectively decreased ZBP1 expression." (PMID 41392977, 2025). "These DLL4+ neutrophils significantly induce pulmonary endothelial cell PANoptosis, exacerbate acute lung injury, and amplify systemic inflammation in sepsis." (PMID 41392977, 2025). "To investigate the role of DLL4+ neutrophils in sepsis-induced ALI, we assessed their impact on lung endothelial cells." (PMID 41392977, 2025). "eCIRP stimulates neutrophil DLL4 expression via TLR4, leading to the elevated DLL4+ neutrophil phenotype in the blood and lungs in sepsis." (PMID 41392977, 2025). "In this study, we have identified a distinct DLL4+ neutrophil phenotype that promotes ALI in sepsis." (PMID 41392977, 2025). "In summary, our study is the first to identify DLL4+ neutrophils as a distinct neutrophil phenotype during sepsis." (PMID 41392977, 2025). "In this study, we investigated how eCIRP induces DLL4 expression on neutrophils to promote endothelial cell PANoptosis in sepsis." (PMID 41392977, 2025). "We also explored the mechanisms by which DLL4+ neutrophils exacerbate endothelial barrier dysfunction and ALI and demonstrated the potential of developing an inhibitor to mitigate DLL4+ neutrophil–induced endothelial cell PANoptosis, aiming to reduce sepsis severity." (PMID 41392977, 2025). "We further investigated whether NDI could mitigate pulmonary endothelial PANoptosis induced by DLL4+ neutrophils in sepsis." (PMID 41392977, 2025). "The identification of the role of the Notch1-DLL4 axis, facilitated by neutrophil–endothelial cell crosstalk within the pulmonary microenvironment, is crucial for understanding the development of ALI and positions DLL4-expressing neutrophils as a potential therapeutic target in sepsis-induced ALI." (PMID 41392977, 2025). "Similarly, changes in expression of notch ligands, specifically Dll4, are observed in endothelial cells during sepsis and in the atherosclerotic plaques." (PMID 41244563, 2025). "DLL4+ neutrophils induce pulmonary endothelial cell PANoptosis in sepsis." (PMID 41392977, 2025). "Our results demonstrate that eCIRP, a new DAMP, promotes DLL4+ neutrophils, which induce lung endothelial cell PANoptosis via the Notch1-DLL4 pathway, exacerbating ALI and increasing mortality in sepsis." (PMID 41392977, 2025). "Thus DLL4+ neutrophils were markedly elevated in sepsis and may contribute to ALI pathophysiology." (PMID 41392977, 2025). "To assess the status of DLL4+ neutrophils in sepsis, we performed a cecal ligation and puncture (CLP) model of sepsis." (PMID 41392977, 2025). "In this study, we report the discovery of a unique neutrophil subpopulation with high DLL4 expression, induced by extracellular cold-inducible RNA-binding protein (eCIRP)—a key DAMP in sepsis." (PMID 41392977, 2025).
Sepsis (continued). "This striking improvement underscores the critical role of this pathway in sepsis-induced lethality and highlights its potential as a therapeutic target even without DLL4+ PMN infusion in sepsis." (PMID 41392977, 2025).
skin papilloma (3 papers, 2015 to 2021). A benign papillary neoplastic growth on the skin composed of epithelial cells and a fibrous stalk. "We observed that Dll4 down-regulation promotes productive angiogenesis, although with less mature vessels, in chemically-induced pre-cancerous skin papillomas stimulating their growth." (PMID 26314892, 2015). "Our results demonstrate that endothelial Dll4 overexpression reduces the growth of LLC xenografts, autochthonous chemically-induced skin papillomas and RT2 insulinomas." (PMID 28288569, 2017).
acute lymphoblastic leukemia (2 papers, 2020 to 2022). Leukemia with an acute onset, characterized by the presence of lymphoblasts in the bone marrow and the peripheral blood. "Studies have shown that, overexpression of the Notch signaling ligand DLL4 (delta-like 4) in endothelial cells can promote T-ALL (T-cell acute lymphoblastic leukemia) cells to exit dormancy by binding to the Notch3 receptor on T-ALL cells, and this overexpression of DLL4 can be induced by VEGF." (PMID 35965504, 2022).
Alagille syndrome (2 papers, 2025). "Lastly, an unanswered question is how variants in RBPJ, which is the sole transcription factor downstream of all NOTCH receptors, cause an N1/DLL4 syndrome (AOS) but not an N2/JAG1 syndrome (Alagille syndrome)." (PMID 41055965, 2025).
allergic asthma (2 papers, 2013 to 2017). A asthma with a basis in a pathological type I hypersensitivity reaction. "We investigated whether Notch ligands, Jagged1 and DLL4, exert differential effects in OVA-induced allergic asthma." (PMID 28262821, 2017).
colitis (2 papers, 2014 to 2021). Inflammation of the colon. "Double staining with Hes1 confirmed that a rare population of Dll1+ve IECs, as well as the dominant Dll4+ve IECs clearly located adjacent to Hes1+ve IECs within the elongated crypts of the DSS-colitis mice." (PMID 24860699, 2014). "Quantitative analysis confirmed that number of Dll1+ve IECs significantly decrease, whereas that of Dll4+ve IECs significantly increase in DSS-colitis mice, compared to control mice." (PMID 24860699, 2014). "We also found that the dominance of Dll1+ve or Dll4+ve IECs within the colonic crypt significantly shifts to Dll4+ve IECs in DSS-colitis mice." (PMID 24860699, 2014). "Conversely, a striking increase in the number of Dll4+ve IECs was observed in the crypts of those DSS-colitis mice, suggesting that a distinct regulation of Dll1 and Dll4 expression exists under the inflammatory environment." (PMID 24860699, 2014). "Also, the analysis showed that both Dll1+ve and Dll4+ve IECs that were found in the DSS-colitis mice maintain their expression of ATOH1." (PMID 24860699, 2014). "Therefore, we examined the expression of Dll1 and Dll4 in tissues of DSS-colitis mice." (PMID 24860699, 2014). "Our results showed that the expression of angiocrine signaling-related genes, such as Cd31 and Dll4, was significantly decreased in the DSS + HF group, further implying that DSS-induced colitis enhanced the disruption of angiocrine signaling in the liver." (PMID 34795650, 2021).
colorectal adenoma (2 papers, 2009 to 2020). An adenoma that arises from the colon or rectum. "We investigated mRNA expression of four Notch receptors (Notch1–4), five ligands (Jag1, Jag2, Dll1, Dll3, and Dll4), and four target genes (Hes1, Hes5, Hey1, and Hey2) using highly specific TaqMan gene expression assays in colorectal adenomas and cancers." (PMID 32211044, 2020). "In the whole sections, >10% of the malignant epithelial cells of the colorectal adenomas and adjacent adenocarcinomas expressed Dll4 in 8 of 12 cases (median 30%, range 10–60%)." (PMID 19844231, 2009). "In regions of both colorectal adenomas and adenocarcinomas, high levels of Dll4 expression were observed in neoplastic epithelial cells with goblet cell differentiation." (PMID 19844231, 2009). "The pattern of Dll4 expression by in situ hybridisation matched the immunohistochemistry results for the 12 colorectal adenomas with adjacent adenocarcinoma." (PMID 19844231, 2009).
coronary artery disease (2 papers, 2017 to 2022). "Disruption of Pofut1, which controls the strength of NOTCH ligand binding, or Dll4, results in coronary artery anomalies that lead to early-onset ischemic heart disease." (PMID 28924218, 2017).
Ewing sarcoma (2 papers, 2011 to 2020). A small round cell tumor that lacks morphologic, immunohistochemical, and electron microscopic evidence of neuroectodermal differentiation. "In Ewing sarcoma mouse models, it has been demonstrated that inhibition of DLL4 expression results in reduced numbers of bone marrow derived pericytes/ vascular smooth muscle cells (vSMCs) and less functional vessels than tumors of control-treated mice." (PMID 32373218, 2020). "Twelve of fourteen human Ewing's sarcoma samples, including metastatic lesions, had similar patterns of DLL4 expression by perivascular cells." (PMID 21785569, 2011). "The Notch ligand Delta like ligand 4 (DLL4) is essential for the formation of BM-derived pericytes/vSMC in Ewing's sarcoma in vivo." (PMID 21785569, 2011). "In addition to VEGF, DLL4 is currently being evaluated as a therapeutic target for the treatment of solid tumors, including Ewing's sarcoma." (PMID 21785569, 2011). "DLL4 is expressed by the BM-derived pericytes/vSMC in Ewing's tumors." (PMID 21785569, 2011). "DLL4 may therefore be a therapeutic target for the treatment of patients with Ewing's sarcoma, as indicated by the tumor growth inhibition in tumors when DLL4 was blocked." (PMID 21785569, 2011). "Additionally, while DLL4-Notch signaling is important for BM cell differentiation into pericytes/vSMCs, the relative contribution of other pericyte/vSMC differentiation factors, such as transforming growth factor beta (TGF-β) and PDGFR-β, has not been evaluated in Ewing's sarcoma." (PMID 21785569, 2011).
Hepatic failure (2 papers, 2023). "Transplantation of human bone marrow mesenchymal stem cells (hBMSCs) into immunodeficient mice with fulminant hepatic failure induced restoration of the damaged liver by enhancing hBMSCs differentiation into cholangiocyte via delta ligand-like 4 (DLL4) activation." (PMID 37426664, 2023).
Insulin resistance (2 papers, 2014 to 2021). Increased resistance towards insulin, that is, diminished effectiveness of insulin in reducing blood glucose levels. "Several recent studies have highlighted how control of macrophage signaling, via c-Jun N-terminal kinase (JNK) and Notch ligand Delta-like 4 (DLL4), affects inflammation and insulin resistance." (PMID 24892847, 2014).
insulinomas (2 papers, 2010 to 2017). "Histologicaly, microvessel density assessed by immunostaining of PECAM was significantly increased in PBS treated Dll4+/- tumors compared to PBS treated Dll4+/+ insulinomas, while sEphB4-Alb treatment in RT2 Dll4+/+ mice caused a statistically significant decrease of tumor vessel density." (PMID 21092311, 2010). "In comparison, RT2 Dll4+/- insulinoma showed a 1.8-fold increase in the density of PECAM-positive areas (p < 0.05) and formed atypical networks lacking vessel hierarchy or symmetry but displaying pronounced branching and multiple interconnections." (PMID 21092311, 2010). "On average, RT2 Dll4+/- insulinoma volume and overall tumor burden, calculated as a sum of tumor volumes per mouse, were reduced by approximately 50% compared to the control animals." (PMID 21092311, 2010). "Surprisingly, increased PDGFR-β levels were identified in RT2 Dll4+/- vs. RT2 Dll4+/+ insulinomas even though there was a prominent reduction in mural cell recruitment to the vessels." (PMID 21092311, 2010). "Relative to Dll4+/+ insulinomas, Dll4+/- tumors showed an approximately 50% reduction in Dll4 mRNA levels, as expected, as well as reduced Hey2 expression, consistent with a reduction in Notch signaling." (PMID 21092311, 2010). "Angiopoietin receptor Tie2 as expected was decreased in Dll4+/- compared to Dll4+/+ insulinomas." (PMID 21092311, 2010). "In addition, VEGFR3 is induced in insulinomas of Dll4+/- RT2 mice compared to the Dll4+/+ RT2 littermates." (PMID 21092311, 2010). "To confirm that Dll4 overexpression results in tumor suppression independently of neoplasm histological type, we also studied its impact on autochthonous RT2 insulinoma development." (PMID 28288569, 2017). "Thus, amplified Dll4/Notch signaling repeated its effects on tumor growth and modified vascular response in RT2 insulinomas in the same way it previously influenced angiogenesis in LLC xenografts and chemically-induced skin tumors." (PMID 28288569, 2017). "Histologicaly, Dll4 overexpression in RT2 D4OE mice was found to decrease insulinoma endothelial density by 32% (p < 0.05), increase α-SMA-positive mural cell coverage by ~20% (p < 0.05) and result in improved lectin perfusion by 27% (p < 0.05) in relation with RT2 D4BE insulinomas." (PMID 28288569, 2017). "Furthermore, the simultaneous suppression of Dll4/Notch and Ephrin-B2/EphB4 signaling in sEphB4-Alb treated RT2 Dll4+/- mice drastically reduced the vessel diameters and their mural cell coverage, even though the total PECAM-positive area apparently similar to PBS-treated Dll4+/+ insulinomas." (PMID 21092311, 2010).
ischemic stroke (2 papers, 2022). A stroke disorder caused by obstruction of blood flow to the brain, due to thrombotic (local blood clot formation) or embolic (due to a blood clot or other material traveling from another site) event. "Furthermore, Sema3E/PlexinD1 signaling inhibits postischemic angiogenesis by regulating endothelial DLL4 and filopodia formation in a rat model of ischemic stroke." (PMID 36091595, 2022).
latent infection (2 papers, 2009 to 2016). "We then performed linear regression analysis to determine if there was a direct correlation between cytokine production and DLL4 expression in both latent infection and active TB disease." (PMID 27933064, 2016). "Our work suggests that KSHV can establish differential upstream signaling events leading to the expression of DLL4 and JAG1 coincident with lytic and latent infection respectively." (PMID 19816565, 2009).
malaria (2 papers, 2017 to 2023). Malaria is a serious and sometimes fatal disease caused by a parasite that commonly infects a certain type of mosquito which feeds on humans. "We also found that plasma exosomes from malaria-infected mice reduced DLL4 expression in ECs." (PMID 28650446, 2017).